RIPK1 (receptor interacting serine/threonine kinase 1)
Diseases named in the same sentence as RIPK1 in open-access papers (continued):
Sharing a sentence is not in itself a finding about the gene and the disease.
systemic lupus erythematosus (5 papers, 2016 to 2025). An autoimmune multi-organ disease typically associated with vasculopathy and autoantibody production. "Inhibiting RIPK1 has shown efficacy in models of NET-driven diseases, including autoimmune vasculitis, venous thrombosis, and Systemic Lupus Erythematosus (SLE)." (PMID 40007541, 2025).
abdominal aortic aneurysm (4 papers, 2017 to 2021). Enlargement and ballooning of the vessel that supplies arterial blood to the abdomen, pelvis and legs. "Wang and his colleagues observed that the expressions of RIPK1 and RIPK3 were elevated in human abdominal aortic aneurysm, especially medial smooth muscle cells, and the level of RIPK3 was also elevated in the mouse model of abdominal aortic aneurysm." (PMID 34977874, 2021).
cholangiocarcinoma (4 papers, 2020 to 2024). A carcinoma that arises from the intrahepatic biliary tree (intrahepatic cholangiocarcinoma) or from the junction, or adjacent to the junction, of the right and left hepatic ducts (hilar cholangiocarcinoma). "Furthermore, targeting RIPk1/3 using CRSIPR-Cas9 system in cholangiocarcinoma established that targeting RIPK1 results in suppressed TLR3 ligand and Smac mimetic induced apoptosis and necroptosis." (PMID 39075259, 2024). "For instance, researchers have found that gemcitabine could induce RIPK1/RIPK3/MLKL-dependent necroptosis in cholangiocarcinoma cells." (PMID 35756487, 2022).
frontotemporal dementia (4 papers, 2021 to 2025). Frontotemporal dementia (FTD) comprises a group of neurodegenerative disorders, characterized by progressive changes in behavior, executive dysfunction and language impairment, as a result of degeneration of the medial prefrontal and frontoinsular cortices. "Furthermore, human TBK1 mutations that cause elevated RIPK1 activity and neuroinflammation in the central nerve system result in ALS/frontotemporal dementia (FTD) comorbidity." (PMID 34862394, 2021). "Mechanistically, TBK1 inactivates RIPK1 by phosphorylating RIPK1 at Thr189, and loss of TBK1 boosts RIPK1 activation and aggravates late-onset ALS/frontotemporal dementia-like pathology, providing insights on intermolecular regulation between TBK1 and RIPK1 in ALS." (PMID 40328798, 2025).
Hepatic fibrosis (4 papers, 2021 to 2023). The presence of excessive fibrous connective tissue in the liver. "Inhibition of RIPK1 also attenuated hepatic fibrosis and significantly reduced the levels of hydroxyproline." (PMID 37169760, 2023).
Hepatic steatosis (4 papers, 2022 to 2023). Steatosis is a term used to denote lipid accumulation within hepatocytes. "RIPK1 activation has been shown to promote hepatic steatosis and hepatic inflammation in a conventional high-fat diet (HFD)-induced NAFLD model." (PMID 37169760, 2023). "We further investigated the role of SENP1-mediated RIPK1 suppression in the pathogenesis of NAFLD by feeding mice with HFD for 16 weeks to induce moderate hepatic steatosis, hepatic inflammation, liver damage, and fibrosis." (PMID 36414671, 2022). "The correlation between RIPK3 and hepatic steatosis is well established, and RIPK1/MLKL axis appears to be a considerable pathway of hepatic lipid deposition." (PMID 35083817, 2022). "Interestingly, inhibiting RIPK1 reduced alcohol‐induced liver steatosis, inflammatory gene expression and neutrophil recruitment." (PMID 35083817, 2022). "For example, RIPA-56, a highly specific inhibitor of RIPK1, reduced high fat diet (HFD)-induced liver steatosis and injury partly through an increase in mitochondrial respiration." (PMID 38161978, 2023).
HIV-1 infection (4 papers, 2014 to 2021). The type species of lentivirus and the etiologic agent of acquired immunodeficiency syndrome (AIDS). "The role of RIPK1 degradation during HIV-1 infection of macrophages needs further investigation." (PMID 34824340, 2021). "Based on these observations, we wondered whether PR could mimic the role of caspase-8 in attenuating type I IFN signaling by directly cleaving RIPK1 during HIV-1 infection." (PMID 26297639, 2015). "Whether HIV-1 infection leads to the formation of a RIPK1/RIPK3 complex that could promote NLRP3 inflammasome activation remains to be elucidated." (PMID 26297639, 2015). "Supporting evidence include reports showing that HIV-1 PR specifically cleaves other serine/threonine kinases, including the NDR1 and NDR1 kinases, receptor-interacting protein kinase 1 (RIPK1), and RIPK2 in CD4+ T cells during HIV-1 infection." (PMID 26982200, 2016). "RIPK1 and RIPK2 were cleaved during HIV-1 infection of T cell lines or primary activated CD4+ T cells." (PMID 26297639, 2015). "Taken together, our results demonstrate cleavage of RIPK1 in T cell lines and primary CD4+ T cells during HIV-1 infection." (PMID 26297639, 2015). "Having established that PR cleaves RIPK1 and RIPK2 during HIV-1 infection, we sought to determine whether cleavage of RIPKs deregulated host processes that may impact virus replication." (PMID 26297639, 2015). "Having established that ectopically expressed or purified HIV-1 PR can cleave RIPK1 and RIPK2 in various cell types, we next asked whether RIPK1 and RIPK2 are cleaved during HIV-1 infection." (PMID 26297639, 2015). "Further, because the specific combination of RIPK1 and RIPK3 lead to necroptosis and the nec-1 can inhibit their interaction, we have also performed RIPK1/RIPK3 co-IP to clarify that necroptosis occurs during HIV-1 infection." (PMID 24714696, 2014).
lymphoma (4 papers, 2015 to 2023). A malignant (clonal) proliferation of B- lymphocytes or T- lymphocytes which involves the lymph nodes, bone marrow and/or extranodal sites. "We compared RIPK1 and RIPK3 protein, and mRNA expression in 17 different epithelial cancer and lymphoma cell lines and found that RIPK1 mRNA and protein were ubiquitously detected in all cancer cell lines tested." (PMID 25675296, 2015). "While posttranslational mechanisms that prevent CYLD and RIPK1 from becoming death-signaling molecules in the early death checkpoint are crucial to lymphoma cell survival, the induction of NFκB-dependent prosurvival genes in the late checkpoint is also integral and this has been widely studied." (PMID 32024820, 2020).
multiple myeloma (4 papers, 2019 to 2025). "We analysed six single-nucleotide polymorphisms in a population of patients with multiple myeloma (n = 205) and healthy volunteers (n = 100): RIPK1 rs2272990, RIPK1 rs9391981, RIPK3 rs724165, RIPK3rs3212243, MAPKAPK2, rs45514798 and MAPKAPK2 rs4073250." (PMID 40508046, 2025). "The tag SNP of RIPK1 in Caucasian, rs9391981, was associated with a decreased risk for multiple myeloma in a population residing in Connecticut." (PMID 37996860, 2023). "Further studies may be required to establish if there is any association between RIPK1 SNPs and response to proteasome inhibitors affecting necroptosis in multiple myeloma patients." (PMID 40508046, 2025). "In the present study, we showed that SNPs located in genes encoding RIPK1, RIPK3 and MAPKAPK2 may be associated with the clinical parameters of multiple myeloma." (PMID 40508046, 2025). "We hypothesise that SNPs located in RIPK1, RIPK3 and MAPKAPK2 could be associated with multiple myeloma survival, treatment outcome and clinical parameters." (PMID 40508046, 2025). "The associations we observed between polymorphisms in RIPK1, RIPK3, and MAPKAPK2 genes and patient survival and treatment response reflect deeper biological relationships between genetic variants of necroptosis pathways and the pathophysiology of multiple myeloma." (PMID 40508046, 2025). "Inhibiting necrosome complex constituents RIPK1/3 did not protect against Ad[CE1A]-induced death, but inhibiting MLKL, the final mediator of necroptosis, significantly protected myeloma cells." (PMID 40247106, 2025). "Pharmacological inhibition of RIPK1 (Necrostatin-1 (Nec-1)) and RIPK3 (GSK-872) (data not shown) failed to protect myeloma cells from Ad[CE1A]-induced cell death." (PMID 40247106, 2025).
non-alcoholic fatty liver disease (4 papers, 2020 to 2025). "Here the authors report that a SUMO-specific protease, SENP1, deSUMOylates RIPK1 and inhibits cell death in a mouse model of non-alcoholic fatty liver disease." (PMID 36414671, 2022). "Although clinical applications of MLKL inhibitors remain limited, elevated systemic levels of RIPK1 and MLKL have been reported in patients with inflammatory conditions such as non-alcoholic fatty liver disease, highlighting their pathophysiological relevance." (PMID 41012357, 2025).
non-small cell lung carcinoma (4 papers, 2019 to 2022). A group of at least three distinct histological types of lung cancer, including non-small cell squamous cell carcinoma, adenocarcinoma, and large cell carcinoma. "It is worth noting that, in Non-Small Cell Lung Cancer (NSCLC) lines, which resist to TRAIL-induced death, TRAIL can instead promote migration via a RIPK1-Src-STAT3 pathway." (PMID 32365592, 2020).
osteoarthritis (4 papers, 2019 to 2025). A noninflammatory degenerative joint disease occurring chiefly in older persons, characterized by degeneration of the articular cartilage, hypertrophy of bone at the margins and changes in the synovial membrane. "Moreover, we also discovered that LIPUS decreased the expression of YAP by restoring the impaired autophagy capacity and inhibiting the binding between YAP and RIPK1, thereby delaying the progression of osteoarthritis." (PMID 38493143, 2024). "We also demonstrated that the expression of YAP was increased in osteoarthritis chondrocytes and YAP could interact with RIPK1, thereby regulating the NF-κB signal pathway and influencing inflammation." (PMID 38493143, 2024).
osteoporosis (4 papers, 2021 to 2025). A condition of reduced bone mass, with decreased cortical thickness and a decrease in the number and size of the trabeculae of cancellous bone (but normal chemical composition), resulting in increased fracture incidence. "Collectively, RIPK1 kinase may serve as a new target for the development of therapeutic drugs for osteoporosis." (PMID 36339402, 2022). "are examining the expression of RIPK1 and RIPK3 in GIOP rats after glucocorticoid (dexamethasone) injection to induce osteoporosis pharmacologically." (PMID 36339402, 2022). "Necrostatin-1 (NEC1) is a receptor-interacting protein kinase-1 (RIPK1)-targeted necroptosis inhibitor that has shown potential therapeutic effects in various skeletal system diseases, including cartilage thinning, osteonecrosis, osteoporosis, and OA (L. Cao and Mu, 2021)." (PMID 41487948, 2025). "Studies have found that excessive alcohol consumption leads to activation of RIPK1/RIPK3/MLKL signaling which increases necrotrophic apoptosis of osteoblasts and reduces osteogenic differentiation and bone formation in vivo and in vitro, leading to the development of osteoporosis." (PMID 35118075, 2021).
ovarian tumor (4 papers, 2012 to 2025). "There was no expression of RIPK1 or phospho-MLKL in ovarian tumour tissues collected from mice that had been treated with placental micro- or nano-EVs." (PMID 37503762, 2023).
polyarthritis (4 papers, 2021 to 2024). "Humans with RIPK1 deficiency develop recurrent infections, IBD, and progressive polyarthritis, indicating that RIPK1 functions are essential for maintaining tissue homeostasis." (PMID 33273695, 2021). "RIPK-1 protein deficiency and the possibility of larger copy-number variants evading detection during routine testing should be considered in the presence of VEO-IBD, polyarthritis, and recurrent infections." (PMID 38676845, 2024).
acute myeloid leukemia (3 papers, 2019 to 2022). Acute myeloid leukemia (AML) is a group of neoplasms arising from precursor cells committed to the myeloid cell-line differentiation. "FLT3 is the most common mutation site in acute myeloid leukemia, and the mutation of FLT3 increased the expression level of RIPK1 and the sensitivities of necroptosis." (PMID 35864548, 2022). "Moreover, primary ALL and acute myeloid leukemia (AML) samples undergo RIPK1-dependent death upon SMAC mimetics treatment." (PMID 30941349, 2019).
aneurysm (3 papers, 2020 to 2024). Bulging or ballooning in an area of an artery secondary to arterial wall weakening. "Pharmacological inhibition of RIPK‐1 with Nec‐1 stabilized pre‐existing aneurysms in an elastase‐induced AAA model by diminishing inflammation and promoting connective tissue repair." (PMID 38873710, 2024). "Elevated levels of RIPK3 and RIPK1 in human abdominal AA (AAA), particularly in α‐SMA+ VSMCs, indicate the involvement of necroptosis in aneurysm pathogenesis." (PMID 38873710, 2024).
autoinflammatory syndrome (3 papers, 2022 to 2025). A group of disorders of the innate immune system characterized by attacks of seemingly unprovoked inflammation without significant levels of either autoantibodies or autoreactive T cells more characteristic of autoimmune disease. "Patients carrying Ripk1 mutations rendering RIPK1 resistant to caspase-8 cleavage develop an autoinflammatory syndrome." (PMID 38734851, 2024). "Biallelic Ripk1 mutations in humans are associated with T cell dysbiosis and autoinflammatory syndromes." (PMID 38734851, 2024). "Consequently, mice and patients with mutations in the caspase-8 cleavage site of RIPK1 develop an autoinflammatory syndrome characterized by excessive RIPK1-dependent cell death." (PMID 40307618, 2025).
breast tumor (3 papers, 2015 to 2019). "The sensitivity of our assays is highlighted by the reproducible detection of TNF-α-induced RIPK1 activation and the detection of 46 T-loop phosphorylation sites from a breast tumor needle biopsy." (PMID 31521607, 2019).
cardiomyopathy (3 papers, 2022 to 2025). A disease of the heart muscle or myocardium proper. "Genetic inactivation of RIPK1 rescues TAB2 deficiency–induced cardiomyopathy in vivo." (PMID 34990405, 2022).
chronic periodontitis (3 papers, 2019 to 2020). A chronic inflammatory process that affects the tissues that surround and support the teeth. "Similarly, RIPK1 also showed prominent upregulation in tissues with periodontitis compared with normal control samples." (PMID 30814594, 2019). "In summary, RIPK1/3-MLKL-dependent necroptosis was involved in the progression of periodontitis, and the P. gingivalis-induced death of immune cells in the periodontal milieu not only led to DAMP-induced tissue damage but also to the further loss of periodontal stem cells in the periodontium." (PMID 30814594, 2019). "In vivo, elevated levels of the necroptosis markers, in particular RIPK1 and MLKL, were observed in gingival tissues collected from patients with untreated chronic periodontitis; but so far, the periodontal ligament cells are supposed to undergo necroptosis." (PMID 32630157, 2020). "Semiquantitative Western blot analysis showed that RIPK1, pRIPK3, MLKL, pMLKL and FLIPL levels were significantly higher in the chronic periodontitis group than in the normal controls." (PMID 30814594, 2019). "By modulating both the TRIF-dependent alternate and RIPK1-dependent classic necroptosis, CDK9 inhibition may enhance survival of immune cells and reduce release of DAMPs during periodontitis progress." (PMID 31758083, 2019). "In addition, decreased RIPK1 and RIPK3 can be observed in the periodontal tissue in the experimental periodontitis model after FVD treatment, further indicating that CDK9 may modulate necroptosis during periodontitis progression." (PMID 31758083, 2019).
Crohn disease (3 papers, 2021 to 2025). A gastrointestinal disorder characterized by chronic inflammation involving all layers of the intestinal wall, noncaseating granulomas affecting the intestinal wall and regional lymph nodes, and transmural fibrosis. "Given that T cells are central to driving intestinal pathology in both Crohn’s disease and celiac disease, it is essential to investigate the role of RIPK1 in T cells and its contribution to maintaining intestinal homeostasis." (PMID 40307618, 2025). "Additionally, this study reveals how intestinal T cell perturbation through RIPK1 ablation can result in specific pathological features observed in human enteropathies, such as celiac disease, autoimmune enteropathy and Crohn’s disease." (PMID 40307618, 2025). "Immunofluorescence RIPK1 staining in rectal biopsies demonstrated no expression for Patient 1 and minimal expression for Patient 2, compared to controls and patients with active Crohn’s disease." (PMID 36466854, 2022).
depression (3 papers, 2021 to 2023). "In order to explore the possible mechanism of necroptosis in the mouse model of depression, the expressions of RIPK1, RIPK3, MLKL, p-MLKL were detected by western blot assay." (PMID 34867405, 2021). "In the current study, we found a reduced number of astrocytes and elevated levels of necroptosis kinases, including RIPK1/p-RIPK1, RIPK3/p-RIPK3, and MLKL/p-MLKL, in hippocampal astrocytes of depression-like behavior mice." (PMID 36686688, 2022). "We raised another hypothesis that fluoxetine may inhibit RIPK1/RIPK3/MLKL-induced necroptosis of astrocytes in MDD to protect astrocyte injury and to reduce proinflammatory cytokines (such as IL-6 and TNF-α) induced by depression disorder." (PMID 36686688, 2022).
diabetic cardiomyopathy (3 papers, 2022 to 2025). Diabetic cardiomyopathy is a disorder of the heart muscle in people with diabetes. "In summary, Nec-1-dependent inhibition of RIPK1/RIPK3 is a viable treatment strategy for diabetic cardiomyopathy." (PMID 35165268, 2022). "Silencing RIPK1/RIPK3 significantly reduces autophagy-associated proteins such as LC3-II and p62, indicating that the RIPK1/RIPK3 pathway is crucial for regulating autophagic flux in diabetic cardiomyopathy." (PMID 40004130, 2025). "However, the role of the RIPK1/RIPK3 signaling pathway in myocardial fibrosis and related diabetic cardiomyopathy is still unclear." (PMID 35165268, 2022).
emphysema (3 papers, 2023 to 2025). "Furthermore, RIPK1 deficiency diminishes smoking-induced pulmonary cell apoptosis and necrotic cell death, thereby alleviating airway inflammation, remodeling, and emphysema while also preventing cigarette-induced impairment of mucociliary clearance." (PMID 41369363, 2025). "GSK’547 is a RIPK1 inhibitor that significantly reduces elastase-induced emphysema and lung function decline, diminishes CS-induced peri-bronchial inflammatory cell infiltration, airway collagen deposition, and emphysema-like changes." (PMID 41369363, 2025). "Genetic or pharmacological inhibition of RIPK1 using GSK’ 547 markedly lowered airway inflammation following acute and subacute exposure to CS, reduced apoptosis and necrosis induced by chronic exposure, and mitigated airway remodeling and emphysema." (PMID 41369363, 2025). "Immunohistochemical staining analysis showed that the expression levels of RIPK1, RIPK3, and MLKL in alveolar epithelial cells in the CS group were higher than those in the normal control group, indicating that necroptosis was enhanced in the lungs of mice with emphysema." (PMID 36979417, 2023).
esophageal cancer (3 papers, 2014 to 2023). A primary or metastatic malignant neoplasm involving the esophagus. "Elevated RIPK1 expression significantly leads to cisplatin-induced apoptosis in human esophageal cancer cells." (PMID 37864090, 2023). "More importantly, we demonstrate that RIPK3 is necessary for cisplatin-induced killing of esophageal cancer cells because inhibition of RIPK1 activity by necrostatin or knockdown of RIPK3 significantly attenuates necrosis and leads to cisplatin resistance." (PMID 24959694, 2014). "In contrast, the high expression of TLR3 in KIRC, ACC, MESO, esophageal carcinoma (ESCA), and uterine carcinosarcoma (UCS); FASLG in HNSC, BLCA, and STAD; RIPK3 in COAD; RIPK1 in MESO and KIRP; FAS in ACC; and FADD in THCA was associated with good survival." (PMID 35748782, 2022).